TLN1 (talin 1)
Diseases named in the same sentence as TLN1 in open-access papers (continued):
Sharing a sentence is not in itself a finding about the gene and the disease.
myopathy (3 papers, 2012 to 2023). A disease of the muscle in which the muscle fibers do not function properly. "Mouse mutants of talin 1 or talin 2 perform myopathy and disassembly of the sarcomeres." (PMID 31623094, 2019).
benign tumors (1 paper, 2023). "Our results indicated that the expression of talin-1 was upregulated in the OSC patients than in benign tumors and normal tissue samples." (PMID 37942198, 2023). "Our IHC examination for talin-1 was significantly overexpressed in OSC tissues compared to benign tumors and normal tissues." (PMID 37942198, 2023). "Furthermore, in the current study, benign tumors showed higher expression of talin-1 compared to normal tissues." (PMID 37942198, 2023). "Moreover, using the IHC method, the upregulation of the talin-1 protein was significantly detected in OSC tumors than in benign tumors and normal tissues." (PMID 37942198, 2023). "The expression level of talin-1 was also evaluated in benign tumors and normal tissue samples." (PMID 37942198, 2023). "Thereafter, immunohistochemical (IHC) staining was used to study the expression patterns of the talin-1 protein using 46 paraffin-embedded OSC tissue specimens, 25 benign tumors, and 20 normal tissues, which were assembled in tissue microarrays (TMAs)." (PMID 37942198, 2023). "The mean levels of expression of talin-1 (H score) in OSC, benign tumors, and normal tissue samples were 142, 96, and 35, respectively (P<0.05)." (PMID 37942198, 2023).
heart disease (1 paper, 2023). "TLN1 could induce heart disease via suppressing the PI3K/AKT signaling pathway in zebrafish." (PMID 36845093, 2023).
TLN1 also shares sentences with these, for which no sentence is quoted: glioblastoma (4 papers); migraine (3); osteoporosis (3); adenocarcinoma (2); adenomyosis (2); breast tumor (2); lung squamous cell carcinoma (2); thoracic aortic aneurysm (2); Thrombocytopenia (2); acute monocytic leukemia (1); acute myeloid leukemia (1); Adrenocortical carcinoma (1); age (1); airway hyperresponsiveness (1); Alzheimer disease (1); bladder tumor (1); bone disorder (1); bone marrow failure (1); bronchitis (1); cardiovascular disease (1); cervical squamous cell carcinoma (1); chromosomal instability syndrome (1); chronic lymphocytic leukemia (1); Clear Cell Renal Cell Carcinoma (1); cognitive decline (1); colon adenocarcinoma (1); eczema (1); end-stage renal disease (1); endocervical adenocarcinoma (1); endometrial cancer (1).
A further 37 diseases each share a sentence with TLN1 in 1 paper.